SDHAF1 (succinate dehydrogenase complex assembly factor 1)
Description:
Plays an essential role in the assembly of succinate dehydrogenase (SDH), an enzyme complex (also referred to as respiratory complex II) that is a component of both the tricarboxylic acid (TCA) cycle and the mitochondrial electron transport chain, and which couples the oxidation of succinate to fumarate with the reduction of ubiquinone (coenzyme Q) to ubiquinol. Promotes maturation of the iron-sulfur protein subunit SDHB of the SDH catalytic dimer, protecting it from the deleterious effects of oxidants. May act together with SDHAF3. Contributes to iron-sulfur cluster incorporation into SDHB by binding to SDHB and recruiting the iron-sulfur transfer complex formed by HSC20, HSPA9 and ISCU through direct binding to HSC20.
Synonyms: LYRM8; MC2DN2
Tractability: PROTAC: its protein half-life has been measured.
Gene: Protein-coding gene on chromosome 19 (35,995,188 to 35,996,312, forward strand). Ensembl gene ENSG00000205138.
Subcellular location: Mitochondrion matrix
Subcellular location (Human Protein Atlas): Mitochondria
Pathways (Reactome):
Metabolism: Maturation of TCA enzymes and regulation of TCA cycle
Gene Ontology:
Molecular function: protein binding
Biological process: mitochondrial respiratory chain complex II assembly
Cellular component: mitochondrion; mitochondrial matrix
Genetic constraint (gnomAD): Missense variants: 196 observed, 122.34 expected, observed/expected ratio (o/e) 1.6, 90% interval 1.42 to 1.8. Synonymous variants: 81 observed, 51.44 expected, observed/expected ratio (o/e) 1.57, 90% interval 1.31 to 1.87.
Gene-disease validity (ClinGen):
ClinGen rates the evidence that SDHAF1 causes each of these diseases.
mitochondrial disease (autosomal recessive): Definitive.
Leigh syndrome (autosomal recessive): Limited. A progressive neurological disease defined by specific neuropathological features associating brainstem and basal ganglia lesions.
Homologues: Orthologues: chimpanzee SDHAF1 (97% identical), macaque SDHAF1 (97% identical), dog SDHAF1 (83% identical), rat Sdhaf1 (81% identical), mouse Sdhaf1 (79% identical), pig SDHAF1 (79% identical), rabbit SDHAF1 (79% identical). Paralogues in human: LYRM4 (23% identical).
Diseases named in the same sentence as SDHAF1 in open-access papers:
SDHAF1 is named in the same sentence as 14 diseases in open-access papers, as found by Europe PMC text mining. Sharing a sentence is not in itself a finding about the gene and the disease. The quoted sentences say what the papers report.
Leigh syndrome (2 papers, 2020). "The two main phenotypes associated with Complex II-encoded genes, SDHA, SDHB, SDHD, and the assembly factor SDHAF1 are associated with progressive encephalopathy leukodystrophy, Leigh syndrome, and/or cardiomyopathy." (PMID 33426505, 2020).
colorectal cancer (1 paper, 2024). A primary or metastatic malignant neoplasm that affects the colon or rectum. "SDHAF1 plays a crucial role in linking the citric acid cycle and electron transport chain, while SSH3 has been identified as a potential antigen for developing mRNA-based vaccines against balder urothelial carcinoma (BLCA) and has been associated with colorectal cancer cell invasion and metastasis." (PMID 39161762, 2024).
head and neck paraganglioma (1 paper, 2017). A benign or malignant extra-adrenal paraganglioma arising from paraganglia in the head and neck. "To date, loss-of-function mutations in SDHAF1 (biallelic) and SDHAF2 have been associated with infantile leukoencephalopathy and head and neck paragangliomas, respectively." (PMID 28738844, 2017).
Leukoencephalopathy (1 paper, 2012). This term describes abnormality of the white matter of the cerebrum resulting from damage to the myelin sheaths of nerve cells. "Leukoencephalopathy with accumulated succinate is a key symptom of defective complex II assembly due to SDHAF1 mutations." (PMID 22995659, 2012). "To date, clinical features comprising motor regression with spasticity and neuroradiological features including bilateral leukoencephalopathy with elevated succinate on cerebral proton MRS are the suggestive findings pointing to a SDHAF1 mutation." (PMID 22995659, 2012). "Homozygous mutations of SDHAF1 were detected in all five patients affected by leukoencephalopathy with accumulated succinate, but not in any of the four patients with other, diverse clinical phenotypes." (PMID 22995659, 2012). "We investigated whether SDHAF1 is mutated in our nine patients with complex II deficiency with either SDH-defective leukoencephalopathy or other, diverse clinical phenotypes without leukoencephalopathy." (PMID 22995659, 2012).
myocarditis (1 paper, 2024). Myocarditis is a condition that is characterized by inflammation of the heart muscle (myocardium). "Interestingly, ERRα bound Ndufaf3 and Sdhaf1 more significantly in females with myocarditis compared to males with no prediction for these genes by RNAseq or TRANSFAC." (PMID 39696682, 2024).
Obesity (1 paper, 2019). Accumulation of substantial excess body fat. "The succinate dehydrogenase (SDH) complex (SDHAF1), which encodes a protein essential for the assembly of mitochondrial enzyme succinate dehydrogenase (SDH), the main element of complex II45, was hypermethylated in its promoter region in obesity and further hypermethylated in CRC." (PMID 30911103, 2019).
mitochondrial disease (4 papers, 2015 to 2021). "To date, 16 patients have been documented in the literature with SDHAF1-related mitochondrial disease; a total of seven recessive, homozygous pathogenic variants were identified as causal across this cohort." (PMID 33162331, 2020). "Sdhaf1 gene has been recently discovered in association with infantile leukoencephalopathy, an infantile mitochondrial disease, where it harbors a missense point mutation, underscoring its critical regulatory function." (PMID 26225774, 2015). "Mutations in genes encoding for either structural subunits or assembly factors have been described (SDHA, SDHB, SDHD, and SDH assembly factor 1 (SDHAF1) for mitochondrial diseases; SDHD, SDHC, SDHB, SDHA, and SDHAF2 for hereditary paragangliomas)." (PMID 30030362, 2018).
myopathy (1 paper, 2012). A disease of the muscle in which the muscle fibers do not function properly. "In our cohort, riboflavin treatment was applied in patients #2, #4, and #5 (SDHAF1 mutations) as well as #6 (SDH-defective myopathy with exercise intolerance)." (PMID 22995659, 2012).
SDHAF1 also shares sentences with these, for which no sentence is quoted: acute liver failure (1 paper); cardiomyopathy (1); Dysarthria (1); infection (1); paraganglioma (1); pheochromocytoma (1).